FAM167A (family with sequence similarity 167 member A)
Synonyms: C8orf13; DIORA-1; D8S265
Tractability: No criterion of Open Targets' tractability assessment is met for any kind of drug.
Gene: Protein-coding gene on chromosome 8 (11,421,463 to 11,475,908, reverse strand). Ensembl gene ENSG00000154319.
Subcellular location (Human Protein Atlas): Mitochondria
Gene Ontology:
Molecular function: protein binding
Genetic constraint (gnomAD): Loss-of-function variants: 23 observed, 14.6 expected, observed/expected ratio (o/e) 1.58, 90% interval 1.11 to 1.93. The synonymous counts are far from expectation, so gnomAD's model fits this gene poorly and the ratio says little. Missense variants: 401 observed, 287.54 expected, observed/expected ratio (o/e) 1.39, 90% interval 1.28 to 1.51. Synonymous variants: 174 observed, 121.43 expected, observed/expected ratio (o/e) 1.43, 90% interval 1.27 to 1.62.
Homologues: Orthologues: chimpanzee FAM167A (98% identical), macaque FAM167A (95% identical), mouse Fam167a (83% identical), rabbit FAM167A (83% identical), rat Fam167a (83% identical), dog FAM167A (82% identical), pig FAM167A (78% identical), guinea pig FAM167A (71% identical), tropical clawed frog fam167a (64% identical), zebrafish fam167ab (58% identical), zebrafish fam167aa (50% identical), zebrafish FAM167A (49% identical). Paralogues in human: FAM167B (33% identical), AARD (17% identical), C20orf202 (12% identical).
Diseases named in the same sentence as FAM167A in open-access papers:
FAM167A is named in the same sentence as 17 diseases in open-access papers, as found by Europe PMC text mining. Sharing a sentence is not in itself a finding about the gene and the disease. The quoted sentences say what the papers report.
autoimmune disease (3 papers, 2014 to 2022). A disorder resulting from loss of function or tissue destruction of an organ or multiple organs, arising from humoral or cellular immune responses of the individual to their own tissue constituents. "Interestingly, the noncanonical NF-κB pathway regulates immunity, and its aberrant activation can promote autoimmunity; thus, our findings indicate that FAM167A may cause autoimmune diseases by activating the noncanonical NF-κB pathway." (PMID 35241148, 2022).
Hypertension (1 paper, 2013). The presence of chronic increased pressure in the systemic arterial system. "Among the highly up-regulated genes in the MCA of the hypertension only group compared to sham controls were FAM167A, CERS3 and FAM53C." (PMID 23874591, 2013).
cancer (2 papers, 2017 to 2025). A tumor composed of atypical neoplastic, often pleomorphic cells that invade other tissues. "The genes BLK, FAM167A, STAT1, STAT4, TNPO3, and TNIP1 are associated with AIDs, and CDC37, DDX6, MAPT, STAT1, STAT4, and UBE3A are associated with cancers." (PMID 40429780, 2025).
FAM167A also shares sentences with these, for which no sentence is quoted: diabetes (2 papers); asthma (1); Autoimmunity (1); chronic myeloid leukemia (1); Crohn disease (1); dermatomyositis (1); epilepsy (1); Insulin resistance (1); lupus (1); Obesity (1); polymyositis (1); scoliosis (1); type 1 diabetes mellitus (1); type II diabetes (1).